CD47 (CD47 molecule)
Diseases named in the same sentence as CD47 in open-access papers (continued):
Sharing a sentence is not in itself a finding about the gene and the disease.
lymphoma (93 papers, 2015 to 2026). A malignant (clonal) proliferation of B- lymphocytes or T- lymphocytes which involves the lymph nodes, bone marrow and/or extranodal sites. "While CD47 overexpression is associated with a poor prognosis in solid malignancies, data on its prognostic significance in lymphomas are inconsistent." (PMID 42195403, 2026). "Studies in solid tumors and various hematopoietic malignancies (such as leukemia, lymphoma, and multiple myeloma) have detected CD47 expression and found it associated with poor clinical outcomes, regardless of expression level." (PMID 40104289, 2025). "In an effort to analyze the potential of LILRB1 and CD47 co-blockade to enhance the ADCP activity also of lymphoma-associated macrophages (LAM), MNC were prepared from BM samples from DLBCL patients with BM infiltration." (PMID 36389667, 2022). "Other studies in the literature have also reported findings linking CD47 to tumor growth and metastasis in various types of lymphomas, suggesting that CD47 could potentially serve as a novel diagnostic marker for classical HL." (PMID 40104289, 2025). "To test whether cytotoxicity was affected by CD47-deficiency we performed an in vivo cytotoxicity assay using clearance of NK-sensitive RMA-S lymphoma as a readout." (PMID 31337788, 2019). "Again, removing the CD47 ECD on murine lymphoma cells rendered them protected from phagocytosis, while replacing the CD47 ECD on the cells led to their engulfment." (PMID 41511354, 2025). "RAW 264.7 cells were fluorescently labeled with cell proliferation Dye eFluorTM 670 and then co-cultured with CFSE-positive Daudi lymphoma cells in the presence of either CD47 antibodies or an IgG4 isotype control." (PMID 41383500, 2025). "Based on our results, CD47 is expressed by canine round cell tumors and can be accessed via FC, with higher rates observed in leukemias and MCTs compared to lymphomas." (PMID 39535393, 2024). "Clinically available anti-CD47 therapeutic antibodies include Hu5F9-G4, which was safe and tolerated in phase 1 trials in lymphoma and solid tumors." (PMID 38612926, 2024). "In the realm of targeting CD47 immunotherapy for lymphomas, there are currently 15 CD47 antagonists undergoing clinical studies for treatment." (PMID 39040441, 2024). "It has been demonstrated that CD47 expressing lymphomas have poor outcomes and frequently leads to extra nodal dissemination of the malignant lymphoma cells." (PMID 38322418, 2024). "The surplus material of cellular suspension (from enlarged lymph nodes for lymphoma cases and from the nodule for MCTs) or peripheral blood (for leukemia cases) was tested for CD47 expression via FC." (PMID 39535393, 2024). "We found that lymphoma cell line K299 showed upregulation of CD47 after being exposed for several days to crizotinib (120 nM), reaching higher CD47 levels than the untreated condition at day +11." (PMID 39767726, 2024). "A clinical trial has been initiated to evaluate drugs targeting the CD47-SIRα axis and tislelizumab (an anti-PD-L1 antibody) in lymphoma patients." (PMID 38464520, 2024). "These ongoing clinical trials underscore the growing interest and potential of CD47-SIRPα targeted immunotherapy in the treatment of lymphomas, presenting new avenues for improving patient outcomes." (PMID 39040441, 2024). "IMM0306 has displayed superior tumor cell binding preference and more effective anti-lymphoma activity compared to CD47 monoclonal antibody alone in both in vivo and in vitro studies." (PMID 39040441, 2024). "We evaluated the activity of the 47VHH1H4B anti-CD47 nanobody using an apoptosis assay, specifically targeting the U937 monocytic lymphoma cell line known for its pronounced CD47 surface expression." (PMID 38247566, 2024). "CD47 agents currently entering clinical trials for treatment of hematological malignancies except lymphoma." (PMID 39040441, 2024).
lymphoma (continued). "Here, we report that the apoptotic effect of RTX-IgG2 on lymphoma cells contributes to changes in the tumor cell’s CD47 profile by reducing its overall expression and altering its surface distribution." (PMID 39712032, 2024). "Both MYC and HIF-1A oncogenes have been shown to directly bind the CD47 promoter and induce its transcription in breast, leukemia, and lymphoma models." (PMID 37958404, 2023). "Most interestingly, the three ICs, PD-L1/L2 and CD47 mRNA levels are co-regulated among the cohort of lymphoma PDXs with statistical significance per Spearman’s CC analysis, although the underlying mechanisms still need to be elucidated." (PMID 37012357, 2023). "Here, we review the present usage of CD47 antagonists for the treatment of lymphomas and hematologic neoplasms from the perspectives of structure, function, and clinical trials, including a comprehensive overview of the drugs in development." (PMID 36726125, 2023). "Together, these data confirmed the anti-lymphoma activity of HX009 across both the CD47+ B- and T-cell lymphomas, due to the contribution of the SIRPα fragment in HX009." (PMID 37012357, 2023). "For instance, phase I trials on Hu5F9-G4 (5F9), a humanized IgG4 antibody targeting CD47, for lymphoma, lung cancer, and other cancers have shown its efficacy." (PMID 37545625, 2023). "Myc regulates CD47 and PD-L1 expression in multiple tumor types, including lymphoma, leukemia and liver cancer." (PMID 37066414, 2023). "Several studies suggest that expression of CD47 is a prognostic marker in many different types of cancers, such as leukemia, lymphoma, hepatocellular carcinoma, bladder cancer, NSCLC, leiomyosarcoma, colorectal cancer, and pancreatic neuroendocrine tumors." (PMID 36598153, 2023). "The overexpression of CD47 has been identified as an independent predictor of an unfavorable prognosis in patients with different types of cancer, such as lymphoma." (PMID 37508523, 2023). "CD47 is highly expressed on numerous types of cancer cells, including lymphoma cells, where it serves as an antiphagocytic molecule." (PMID 37508523, 2023). "Here, we provide a summary of CD47 antagonist clinical research frontiers in treating lymphomas and hematological malignancies." (PMID 36726125, 2023). "CD47-blocking antibodies in human trials have demonstrated promising early results in lymphoma that indicate a requirement for combination with a tumor-opsonizing IgG (e.g., anti-CD20, rituximab)." (PMID 35454837, 2022). "The only “monotherapy” to succeed to date against patient tumors is an intratumorally administered SIRPα-IgG1 chimera in fungoides mycosis (a type of lymphoma), with evidence that the IgG1 serves to opsonize while SIRPα binds CD47." (PMID 35454837, 2022). "For example, the combination of rituximab with a CD47 antibody increased ADCP of lymphoma cells by macrophages in vitro and improved the therapeutic efficacy in xenograft models of B-NHL." (PMID 36389667, 2022). "For instance, a first-in-human phase I trial of Hu5F9-G4, a humanized anti-CD47 monoclonal antibody, showed promising activity in advanced solid tumors and lymphomas." (PMID 35837100, 2022). "In a lymphoma mouse model, anti-CD47 antibodies prevented lymphoma cell proliferation and prolonged survival." (PMID 35694254, 2022). "DSP107 also blocked the cross talk of SIRPα with CD47 and triggered phagocytosis in several lymphomas, leukemia, and carcinoma cell lines in vitro." (PMID 35978372, 2022). "Essentially, these in vivo studies have also indicated that the treatment of human NHL-inserted mice with CD47/CD20 BsAbs reduces lymphoma burden and prolongs the OS of mice." (PMID 35978372, 2022). "CD47 promotes chemokine-mediated migration of lymphoma cells and by its blockade, it has been demonstrated that this molecule possesses a notable role in the migration of these cells toward known lymphoma chemo attractants SDF-1α and CXCL13." (PMID 32902664, 2021).
lymphoma (continued). "CD47 is a surface protein expressed on nearly all cancers including lymphomas that provides an anti-phagocytic signal to enable cancer cells to evade macrophage-mediated killing." (PMID 34193230, 2021). "Compared with the commonly used anti-mouse CD47 monoclonal antibody, the produced CD47nb had a higher binding affinity to CD47 on the surface of A20 lymphoma cells." (PMID 34158861, 2021). "Other CD47 blocking antibodies currently in clinical trials enrolling patients with lymphoma include TTI-622 (NCT03530683) and ALX148 (NCT03013218)." (PMID 34193230, 2021). "The clinical results of CD47-SIRPα disruption was evaluated in Phase I trial of Hu5F9-G4 (5F9) (ClinicalTrials.gov identifier: NCT02216409), a humanized IgG4 anti-CD47 antibody in patients with advanced solid tumors and lymphomas." (PMID 34988021, 2021). "As previously discussed, lymphoma cells overexpress CD47, thereby suppressing TAM-mediated phagocytosis and contributing to macrophage dysfunction within the TME." (PMID 33804869, 2021). "CD47 overexpression is often observed in malignant tumor cells, and CD47 blockade was reported to be effective for lymphoma cell clearance." (PMID 33121189, 2020). "In a mouse model of lymphoma, anti-CD47 antibodies prevent lymphoma cell proliferation and prolong survival." (PMID 32082311, 2020). "In their study, treatment of human NHL-engrafted mice with anti-CD47 antibody reduced lymphoma burden and improved survival, while combination treatment with rituximab led to the elimination of lymphoma and cure." (PMID 33015199, 2020). "Taken together, these results suggested that HuNb1-IgG4 or CD47/CD20 BsAb was a promising candidate in the treatment of lymphoma." (PMID 31931812, 2020). "Hu5F9-G4 also blocked the binding of SIRPα on the surface of lymphoma cells to CD47 on the surface of macrophages, thus attenuating the “don't eat me” signals within this cancer cell type." (PMID 32082311, 2020). "The results showed that there were significant decreases in CD47 expression in lymphoma cells exposed to normoxic or hypoxic hWJSC-CM compared to controls." (PMID 32377203, 2020). "Curiously, phagocytosis of CD47 knockout Raji lymphoma cells was similar to the untreated control cells (30.6 ± 3.3% and 37.7 ± 5.4%, respectively)." (PMID 31205227, 2020). "Not surprisingly, HuNb1-IgG4 shows better efficacy of anti-ovarian tumor and anti-lymphoma compared to anti-CD47 Hu5F9-G4 monoclonal antibody at the same doses." (PMID 31931812, 2020). "On the other hand, in patients with lymphoma, a recent phase 1b study showed that CD47 mAb in concert with rituximab showed enhanced effects by enhancing macrophage‐mediated antibody‐dependent cellular phagocytosis." (PMID 31376208, 2019). "For example, combination treatment with rituximab and CD47 antibody led to synergetic elimination of lymphoma in mice model." (PMID 31629410, 2019). "CD47 was highly expressed on lymphoma cells such as Raji (Burkitt lymphoma), MWCL (Waldenstrom macroglobulinemia), and Toledo (Diffuse large B-cell lymphoma) lines when compared to isotype controls." (PMID 31611550, 2019). "CD47 overexpression has been reported in most tumor types, including leukemia, lymphoma, and solid tumors." (PMID 30814491, 2019). "The humanized CD47 ScFv detected CD47 antigen better in lymphoma samples and similarly in other tumor samples (ovarian, gastric cancer (not shown) and less or similarly in normal." (PMID 29065481, 2017). "CD20/CD47 bispecific antibodies reduced lymphoma burden and extended survival of NHL-engrafted mice, hence recapitulating the synergistic effects of antiCD47 and antiCD20 combination therapy." (PMID 28061465, 2017). "We demonstrated that CD47 blockade with TTI-621 increased phagocytosis of lymphoma cells by all macrophage subsets." (PMID 29084248, 2017). "High levels of CD47 found on many types of human cancer, including leukemia, lymphoma, and several types of solid tumor cancers and are often associated with poor prognosis." (PMID 28515726, 2017).
lymphoma (continued). "Blockade of CD47 using TTI-621 significantly increased phagocytosis of lymphoma cells by all macrophage subsets, with M(IFN-γ), M(IFN-γ+LPS) and M(IL-10 + TGFβ) macrophages having the highest phagocytic response." (PMID 29084248, 2017). "The bispecific short-linker construct improved the survival of lymphoma-bearing mice and recapitulated the therapeutic benefit of anti-CD47 and anti-CD20 antibody combination therapy." (PMID 28157217, 2017). "Noteworthy work of Weissman and collaborators in immunodeficient mice has proved preclinical efficacy of anti-CD47 mAbs in a wide range of xenograft models including leukemia, lymphoma, multiple myeloma, and several solid tumors." (PMID 26578962, 2015). "Evorpacept (ALX148), a CD47-blocking agent, showed early signs of activity in aggressive lymphomas and may be explored in RT." (PMID 40943662, 2025). "However, the humanized monoclonal CD47 antibody Hu5F9‐G4 is currently undergoing a phase I clinical trial in patients with advanced solid malignancies or lymphomas, and the results indicate that most toxic reactions are mild to moderate." (PMID 40385528, 2025). "CD47 antagonists currently entering clinical trials for treatment of lymphomas." (PMID 39040441, 2024). "Antibodies targeting CD47 enhance tumor cell phagocytosis to reduce tumor growth in xenograft models and a number of clinical trials of anti-CD47 antibodies and small molecule inhibitors have produced good results in lymphomas." (PMID 39588367, 2024). "Lastly, the expression of the immune-checkpoints PD-L1/L2 and CD47 seemed co-regulated among a panel of lymphoma-derived-xenografts, where HX009 maybe more effective in those with upregulated CD47." (PMID 37012357, 2023). "CD20-CD47SL, a CD47xCD20 BsAb, was observed to selectively bind to dual antigen-expressing lymphoma cells in the presence of an “antigen sink” of RBCs and recapitulated the synergistic effects of anti-CD47 antibody and rituximab combinations in mouse models of NHL." (PMID 36575242, 2023). "In oncology study, CD47 was initially discovered as a tumor antigen in human ovarian cancer, and later was found overexpressed in various lymphomas and hematological tumors, such as non-Hodgkin's lymphomas (NHL), T-cell lymphoma, acute myeloid leukemia (AML) and myelodysplastic syndrome (MDS)." (PMID 36726125, 2023). "It is reasonable to speculate that the expression levels of the targets of HX009, the ICs PD1 or its ligands, PD-L1/2, and CD47, in lymphoma could be important parameters that influence HX009 efficacy." (PMID 37012357, 2023). "We have confirmed anti-lymphoma activity of the tumor cell CD47 targeting as shown in xenograft modeling described in this report, although we have yet to demonstrate direct evidence of the role of Teff CD47 targeting in anti-lymphoma activity." (PMID 37012357, 2023). "It is possible that the observed anti-lymphoma activity from anti-CD47 function of HX009 could be the HX009-SIRPα interaction either with tumor cell CD47 or with the Teff CD47, or both." (PMID 37012357, 2023). "With regard to the potential CD47 targeting MOAs of HX009, the anti-lymphoma effect could be attributed to targeting to CD47 either on tumor cells or on Teff CD47 (or even other immune cells in TME), or on both." (PMID 37012357, 2023). "As demonstrated here, the blockade of LILRB1 in addition to CD47 may offer a possibility further enhancing rituximab-mediated ADCP of lymphoma cells." (PMID 36389667, 2022). "Indeed, T-cell independent abscopal effects upon radiotherapy and CD47 blockade were also observed in a xenograft model of lymphoma (Ramos cells, grown in immunodeficient NSG mice)." (PMID 36411318, 2022). "Analysis of different lymphoma cell lines revealed that the ratio of CD20 to HLA class I cell surface molecules determined the sensitivity to ADCP by the combination of rituximab and an Fc-silent variant of the CD47 antibody magrolimab (CD47-IgGσ)." (PMID 36389667, 2022).
lymphoma (continued). "In contrast, limited TGI (<50%) was observed across solid tumor models treated with 10 mg/kg of ZL-1201, suggesting that CD47 blockade may promote antitumor activities more efficiently in lymphoma than in solid tumors." (PMID 36970051, 2022). "Lymphoma cells shield themselves from TAM phagocytosis via the upregulation of CD47." (PMID 33804869, 2021). "In addition, it is verified that tumor cells overexpress CD47 to escape from immune surveillance in various malignant tumors such as leukemia, lymphoma, breast and colon cancer, and antagonism CD47 has significant anti-tumor effects." (PMID 34776955, 2021). "Mouse A20 lymphoma cells, which are sensitive to CD47 blockade, were used as a positive control." (PMID 31205227, 2020). "Proteomics analysis did not reveal any changes in inward signalling capable of sensitizing lymphoma cells to phagocytosis following CD47 blockade, although it remains possible that antibody binding induced more rapid changes that returned to baseline before analysis." (PMID 31205227, 2020). "Moreover, a recent phase 1b clinical trial combining rituximab with an anti-CD47 therapeutic antibody (Hu5F9-G4) showed promising results in lymphoma patients." (PMID 33552071, 2020). "Using this assay, we investigated whether blocking the interaction between SIRPα and CD47 using SIRPα-Fc enhanced phagocytosis of lymphoma cells by Mo/MΦs." (PMID 31611550, 2019). "A similar approach was recently published, and the respective SIRPabodies, which combine an antiCD20 mAb and the endogenous SIRPα domain, were shown to bind CD20 and CD47 on dual expressing cells, reduce tumor burden and prolong survival in xenograft lymphoma mouse models." (PMID 28061465, 2017). "Such CD47-blocking mAbs were shown to be effective by allowing the decrease of tumor burden in several preclinical cancer models including acute myeloid leukemia, lymphoma and osteosarcoma." (PMID 26578962, 2015). "In addition to disruption of cytolysis, an emerging story in lymphomas is the ability to upregulate CD47, a marker of self, and inhibit phagocytosis of the tumor cell via the CD47-SIRPα pathway in host phagocytes." (PMID 25941795, 2015). "In pre-clinical studies, it has been found that radiotherapy in combination with CD47 blockade could stimulate a potent macrophage-mediated abscopal effect in non-small cell lung cancer, lymphoma, and colon cancer models, leading to tumor control at both the irradiated and non-irradiated site." (PMID 39335665, 2024). "Similarly, our research group conducted a preliminary study showing that an engineered OVV expressing an anti-CD47 nanobody improves efficacy against lymphoma by promoting macrophage phagocytosis of CD47+ tumors and NK-cell-mediated antibody-dependent cellular cytotoxicity." (PMID 37615308, 2023). "IMM0306 is a bispecific antibody that targets CD47 and CD20, and a higher affinity for CD20 results in a better binding preference to malignant B cells and more effective anti-lymphoma activity." (PMID 38464520, 2024). "Similarly to the lymphoma subtype, both ALK-driven NSCLC and neuroblastoma, previously incubated with short-term TKIs (20 h of alectinib or lorlatinib for H3122 and 20 h of lorlatinib for CLB-Ga), were more susceptible to phagocytosis with anti-CD47 mAb during co-culture assay." (PMID 39767726, 2024). "Nevertheless, a humanized monoclonal anti-CD47 (HU5F9-G4) is currently being investigated in phase I clinical trials for the treatment of advanced solid tumors and lymphomas." (PMID 36937442, 2023). "The preclinical data presented herein appears to support the contention that combinations of checkpoint targeted drugs, in this case the dual targeting of PD1 and CD47, may be associated with improved activity in models of lymphoma not historically recognized to be sensitive to PD1 or CD47 blockade." (PMID 37012357, 2023).